CD4 (CD4 molecule)
Diseases named in the same sentence as CD4 in open-access papers (continued):
Sharing a sentence is not in itself a finding about the gene and the disease.
dementia (41 papers, 2007 to 2025). Loss of intellectual abilities interfering with an individual's social and occupational functions. "Liver and kidney disease, congestive heart failure, malignancy, and dementia were negatively associated with CD4 (p-trends all <0.0001)." (PMID 38356736, 2023). "The redox alterations is one of the crucial factors of HIV-1 pathogenicity, such as neurotoxicity and dementia, exhaustion of CD4+/CD8+ T-cells, predisposition to lung infections, and certain side effects of the antiretroviral therapy." (PMID 36934258, 2023). "The most commonly reported risk factors of HIV associated dementia were the level of CD4 count and the clinical stage of disease." (PMID 24969686, 2014). "Furthermore, plasma and cerebrospinal fluid (CSF) anti-CD4 IgG levels of three HIV-associated dementia (HAD) patients were within the elevated CSF anti-CD4 IgG group." (PMID 34985329, 2022). "Furthermore, it has been reported that redox alterations are crucial factors in aspects of HIV-1 pathogenicity such as neurotoxicity and dementia, exhaustion of CD4+/CD8+ T-cells, predisposition to lung infections, and so on." (PMID 33156879, 2020). "The proportions of unstimulated CD4+ TH cell subsets in the PBMCs of dementia patients were similar to controls and consistent with published reference ranges in healthy individuals, including high levels of naïve TH cells persisting into old age." (PMID 40537813, 2025). "We analyzed cells by flow cytometry from two groups to identify associations between CD4+ or CD8+ TEMRAs in peripheral blood and early cognitive decline in a community-based cohort of older individuals based on their clinical dementia rating (CDR)." (PMID 38867294, 2024). "In a further study, utilizing single-cell transcriptomics of the CSF, the authors detected increased expression of CXCR4 in CD4+ T cells in patients with Lewy body dementia, a dementia characterized by α-synuclein deposits in the brain." (PMID 35978442, 2022). "Apart from the possible involvement of astrocytosis on cognitive resilience, the majority of the results obtained in the present work suggest the contribution of peripheral immune cells infiltration, specifically of CD4 positive T cells, to dementia in AD." (PMID 34502030, 2021). "The human leukocyte antigen DR isotype independent Aβ-reactive CD4+ T cells were also increased, while the magnitude of T-cell response showed great variable in different stages of dementia." (PMID 31993048, 2019). "Position 283, close to 281 and also in direct contact with CD4, was already shown as playing a key role in modulating CD4 dependence, macrophage tropism, brain infection and dementia." (PMID 28841647, 2017). "Among them are neurotoxicity and dementia and immune imbalance with the exhaustion of the pool of CD4 T-lymphocytes, as well as lung and cardiovascular disorders." (PMID 27829986, 2016). "We hypothesized that CD4+ TH cells against synaptic proteins may play a role in dementia, given the profound changes of synaptic proteins in the disease." (PMID 40537813, 2025). "Perturbed naive and memory CD4+ T cell subsets have been noted in the peripheral blood of patients with mild AD and dementia, with a lower proportion of naive cells and an increased proportion of effector memory and terminal differentiation effector memory (TEMRA) CD4+ cells." (PMID 37849501, 2023). "Furthermore, intrathecal CD4+ T-cell activation in amyotrophic lateral sclerosis surpassed levels in dementia patients." (PMID 34405141, 2021). "The D386 variant has also been associated with HIV-associated dementia (HAD) and an enhanced macrophage tropism that allows the virus to enter cells that are even expressing low levels of CD4 and CCR5 and this, in turn, increases replication preferentially in the CNS." (PMID 33297399, 2020). "CD4+ TEMRAs may also be important in progressing AD and AD-related dementia." (PMID 38867294, 2024).
dementia (continued). "(b) Percentage of each annotated cell population out of the total number of T cells (CD4+ and CD8+ T cells) from the septum of controls, dementia and MS donors." (PMID 35536009, 2022). "CD4+ T cell accumulation was specific for MS, while the percentage of CD8+ T cells was higher in both MS and dementia compared to controls." (PMID 35536009, 2022). "The two HIV+ groups had similar duration of HIV infection, current plasma RNA levels, nadir and recent CD4 cell counts, percentage of participants on stable combination antiretroviral therapy (cART) regimens, HIV dementia scores, and Karnofsky scales." (PMID 32758262, 2020). "This 35 year old male patient with HAD initially presented with severe dementia (HDS of 2), a CD4+ cell count of 145/μl and a plasma and CSF viral load of 58000 and 450000 viral copies/ml, respectively." (PMID 21083890, 2010). "Dementia patients and both control cohorts had similar frequencies of CD4+ TH cells in PBMCs without antigen stimulation." (PMID 40537813, 2025). "In a longitudinal retrospective study with a longer follow up time CSF neopterin concentration did not predict dementia development in 8 patients compared with matched controls, although these patients had higher CD4 cell count." (PMID 20525234, 2010). "For 14 years without antiretroviral therapy D36 had a stable CD4+ T-cell count, but after April 1994 the subject experienced CD4+ T-cell loss until a diagnosis of HIV-associated dementia (HIVD) was made in December 1998." (PMID 19088897, 2007). "Therefore, we assume that the absence of a strong CD4+ TH cell response to the measured neuronal antigens and the lack of a correlation with dementia argue against a strong CD8+ T cell reactivity." (PMID 40537813, 2025). "Alternatively, this may be secondary to the clinical stability of the participants, reflected by a CD4+ T lymphocytes count > 200 cells/μL, undetectable viral load, absence of dementia, and stable use of HAART." (PMID 33304002, 2020). "The R5 T cell-tropic viruses required high levels of the cellular surface receptor CD4 to enter cells, while macrophage-tropic viruses could enter cells with low levels of CD4, suggesting that HIV-1 can replicate in at least two cell types within the CNS during the course of dementia." (PMID 22007152, 2011). "In contrast, CD8+ TEMRA cells formed immune networks with subsets of CD4+ T cells in the MCI stage of AD, while these inter-relations were absent in controls and dementia patients." (PMID 38658964, 2024). "Their cross-sectional study found no change in total T cells, CD4, CD8, or the ratio of CD4:CD8 cells between the people with probable AD-type dementia and aged-matched controls." (PMID 34239415, 2021).
bacterial pneumonia (40 papers, 2007 to 2025). Acute infection of the lung parenchyma caused by bacteria (e.g., Streptococcus pneumoniae, Haemophilus influenzae, Chlamydia pneumoniae, Mycoplasma pneumoniae, and Legionella pneumophila). "The critical risk factors connected to bacterial pneumonia are recent CD4 T cell count ≤350 cells/mm3, alcoholism, HIV-World Health Organization (WHO) Stage II, a viral load ≥ 150 copies/mL, smoking, old age, and cooking food using firewood in the living room." (PMID 39078837, 2024). "The most important risk factor for bacterial pneumonia in PLHA is the degree of immunosuppression reflected by the CD4 + T-lymphocyte count." (PMID 35672713, 2022). "Gut microbiota composition of HIV-infected patients with bacterial pneumonia is associated with peripheral CD4 counts, airway microbiota composition, and in vitro macrophage dysfunction." (PMID 30857553, 2019). "Major risk factors for bacterial pneumonia in patients with HIV infection include lower CD4+ count, higher viral load, older age, cigarette smoking, lack of cART, interruption of cART, alcohol use, injection drug use, and lack of pneumococcal vaccination." (PMID 23457535, 2013). "Importantly, bacterial pneumonia in that study was also associated with faster time to death, even after adjustment for CD4+ count and cART use." (PMID 23457535, 2013). "Is the association between smoking and bacterial pneumonia or PCP modified by CD4 count?" (PMID 23339513, 2013). "Other risk factors include CD4 cell count <200 cells/microL, CD4 cell percentage <14%, previous episodes of PCP, mucocutaneous candidiasis, recurrent bacterial pneumonia, unintentional weight loss, and high HIV RNA viral load." (PMID 39958093, 2025). "In this study, age groups 18-29 and 30-39, alcohol consumption, recent CD4+ count less than 350 cells/μL, and WHO stage II of HIV infection showed significant association to have bacterial pneumonia." (PMID 31192259, 2019). "Younger age group, the recent number of CD4+ cell count less than 350 cells, alcohol consumption, and WHO stage II of HIV infection showed significant association with bacterial pneumonia." (PMID 31192259, 2019). "Bacterial pneumonia continues to be an important comorbidity in people living with HIV even though anti-retroviral therapy has succeeded in restoring CD4+ cell counts." (PMID 26528246, 2015). "The incidence of bacterial pneumonia was 28.8 (CI: 16.7–49.8) and 16.5 (CI: 9.5–28.4) per 1000 patient-years among patients with <200 and those with 200 to 349 CD4 cells/μL, respectively." (PMID 20126646, 2010). "In our study, the incidence of bacterial pneumonia dramatically increased in patients with a CD4 count <350 cells/μL compared to those with a CD4 count above this threshold." (PMID 20126646, 2010). "The hazard of bacterial pneumonia was higher when CD4 count was <200 cells/μL (HR: 2.98; CI: 1.80–4.94; P<0.001) or between 200 and 349/mm3 (HR: 1.98; CI: 1.25–3.15; P = 0.004) as compared when CD4 count ≥500 cells/μL." (PMID 20126646, 2010). "Our flow cytometry studies indicate that γδ-T cells, and to a lesser extent CD4+ Th17 cells, are important sources of IL-17 during bacterial pneumonia." (PMID 20360853, 2010). "Given the importance of Tfh cells in initiating and maintaining cellular immune responses, it is rational to speculate that the elevation of CD4+ Tfh cells in bacterial pneumonia is accompanied by host immune responses after pathogen infection in the low respiratory sites." (PMID 39911385, 2025). "However, as we have previously found, the airway microbiota is not related to the degree of disease severity (as defined by CD4 cell counts), leading us to consider a role for the gut microbiome in modulating peripheral immune function and response to bacterial pneumonia in these patients." (PMID 30857553, 2019). "Bacterial pneumonia can occur at any stage of HIV disease and at any CD4 cell count." (PMID 39727640, 2024).
bacterial pneumonia (continued). "The lack of substantial CD4+ T cell exhaustion in severe patients indicates that CD4+ T cell exhaustion may not be a significant contributor to severe bacterial pneumonia." (PMID 39757231, 2025).
preeclampsia (40 papers, 2014 to 2026). Preeclampsia is a hypertensive disorder of pregnancy that is characterized by new-onset hypertension with proteinuria presenting after 20 weeks of gestation, and depending on mild or severe forms may initially present with severe headache, visual disturbances, and hyperreflexia. "Numerous studies have shown that immune imbalance mediated by CD4+ T lymphocytes cells and their associated immune products is a key factor in the development of preeclampsia." (PMID 36700203, 2022). "CD4+ Treg cells are of particular interest because of their strong association with preeclampsia, and their potential for therapeutic manipulation." (PMID 30984163, 2019). "In comparison to normal pregnancy, preeclampsia is associated with increased numbers of CD4+CD25highFoxp3+ and decreased numbers and functional activity of CD4+CD25+Foxp3high+ cells." (PMID 30079067, 2018). "In support of the findings associating CD4+CD25high Treg numbers with preeclampsia, circulating levels of CD4+CD25highFoxP3+ Tregs are decreased in preeclamptic women." (PMID 25566263, 2014). "Women with preeclampsia had significantly lower percentages of CD4+FOXP3+ T-regs and concluded that a deficiency of T-regs may play a role in the development of PE." (PMID 37700972, 2023). "Accumulating evidence suggests that preeclampsia is associated with a breakdown of tolerogenic cellular adaptations, including a shift in T cell distributions toward Th1 and Th17 and away from Th2 and regulatory CD4+T cell (Treg) populations." (PMID 31263463, 2019). "We observed a significant decrease in the expression of the CD3, CD8 and CD4 markers in cord blood mononuclear cells in the preeclampsia group." (PMID 42050777, 2026). "The model was specified such that methylation at a given CpG site is conditional upon preeclampsia status with sex, age and blood cell proportions other than neutrophils as covariates (CD4+T and CD8+T, B and Natural Killer cells, monocytes and eosinophils)." (PMID 41286963, 2025). "All these functional DEGs and pathways suggested the preeclampsia-related activation of CD4+ Tn 2 and CD8+ Tn 2 in PE." (PMID 38182876, 2024). "In our study, several novel predictive biomarkers were associated with late-onset preeclampsia, including IDUA, FCGR2B, and CD4." (PMID 38253981, 2024). "Increased CD4+CD25highFoxp3+ cell counts and decreased counts and functional activity of CD4+CD25+Foxp3high+ cell are linked to preeclampsia, compared to a normal pregnancy." (PMID 39355245, 2024). "Between normal pregnancy and preeclampsia, there is a significant difference only in CD4+FOXP3+Tregs." (PMID 39328700, 2024). "In the group of women with preeclampsia compared to the group with gestational hypertension, significantly higher percentages of CD4+CD25+FoxP3+ cells (p = 0.03) and percentages of CD4+CD25+FoxP3+ cells expressing the OX40 antigen (p = 0.001) were observed." (PMID 37887878, 2023). "T cells regulatory (Tregs), a subset of suppressor CD4(+) T cells, play a vital role in the maintaining of immune balance of maternal-fetus interface, which are involved in the development of preeclampsia." (PMID 37020283, 2023). "Reduced concentrations of the SCFA acetate have been reported in women with preeclampsia, and perinatal acetate supplementation is sufficient to promote fetal thymic CD4+ T cell and regulatory T cell development in GF mice." (PMID 37801498, 2023). "Increased pro-inflammatory cytokines and decreased anti-inflammatory cytokines are produced by an imbalance in CD4+T cells in preeclampsia." (PMID 35089126, 2022). "The T helper-17 cells, a subclass of CD4+T cells, are responsible for the secretion of inflammatory cytokine IL-17, which is elevated in preeclampsia." (PMID 35089126, 2022). "To date, CD4+ CM cells are investigated in two complications of pregnancy, i.e., preeclampsia and miscarriages." (PMID 31001255, 2019).
preeclampsia (continued). "The results highlight an important role for STAT5-dependent responses across multiple CD4+T cell subsets that are disrupted prior to the clinical onset of preeclampsia." (PMID 31263463, 2019). "In preeclampsia, slightly, but significantly higher proportions of CD4+ CM cells (CD45RO+CCR7+) were found in peripheral blood from preeclamptic women compared to healthy pregnant women." (PMID 31001255, 2019). "Instead, measurement over time of signaling responses in Tregs (pP38 and pSTAT5) and in CD4+Tbet+Th1 cells (pSTAT5) were among the strongest individual classifiers for preeclampsia." (PMID 31263463, 2019). "In preeclampsia, the number of CD4+CD25high Tregs is decreased in peripheral blood as well as in term placentas." (PMID 25566263, 2014). "In normal pregnancy, the prevalence of CD4+HLA-G+ T cells is high in decidua, while a recent study showed that the expansion of the HLA-G-positive T cell subset is impaired in preeclampsia." (PMID 25566263, 2014). "Our results (higher percentage of CD4+IL-17+) are consistent with reports of increased CD4+IL-17A+ cells in blood and increased RORc mRNA expression in the decidua and PBMCs in women with gestational hypertension, including preeclampsia." (PMID 41156157, 2025). "At the same time, in placental tissue in patients with preeclampsia, on the contrary, a significant decrease of regulatory cells CD4+, CD8+, CD14+, CD56+, CD59+, activation markers CD95+, as well as anti-inflammatory cytokine IL-10, growth factors VEGFR and IGF was detected." (PMID 40647643, 2025). "At the same time, in placental tissue in patients with preeclampsia, on the contrary, a significant decrease in regulatory cells CD4+, CD8+, CD14+, CD56+, CD59+, activation markers CD95+, as well as anti-inflammatory cytokine IL-10, growth factors VEGFR and IGF was detected." (PMID 40647643, 2025). "Remarkably, the preeclampsia symptoms induced in this model are T cell dependent since the RUPP intervention does not cause hypertension and IUGR in T cell deficient athymic rats, and disease can be induced by passive transfer of Th17 effector CD4+ T cells." (PMID 30984163, 2019). "We found that frequencies of cord blood CD4+Foxp3+Helios+ thymic-derived natural Tregs (nTreg) were also significantly lower in preeclampsia (p = 0.035, unpaired t-test), especially in those who did not receive steroid treatment (p = 0.01, one-way ANOVA with Dunnett’s multiple comparisons test)." (PMID 31292453, 2019). "Similarly, adoptive transfer of CD4+ T cells from rats with preeclampsia to normotensive pregnant rats led to BP elevation in the recipient rats." (PMID 28910394, 2017). "And it is therefore speculated that upregulated Lnc-DC promotes the overmaturation of DCs and improves their ability to induce CD4+ T cells to develop into Th1 cells, therefore mediating inflammatory responses and contributing to the pathogenesis of preeclampsia." (PMID 29599646, 2018). "One of the key observations was a significant decrease in the content of CD4+ T helper cells and CD8+ cytotoxic T cells in preeclampsia." (PMID 40647643, 2025). "Clinically, elevated sEng levels are observed in both early and late preeclampsia; high endoglin blocks the action of TGF-β, facilitating CD4+ differentiation toward Th17." (PMID 41156157, 2025). "The results of comparison between preterm preeclampsia and preterm delivery group suggested that B cells, monocytes and neutrophils decreased in preterm preeclampsia and were statistically significant, the number of T cell CD8 and T cell CD4 was increased." (PMID 39148025, 2024). "Among fetal cell types, extravillous trophoblasts (p < 0.001), memory CD4+ T cells (p = 0.007), CD8+ activated T cells (p = 0.005), and natural killer T cells (p = 0.006) were more abundant in preeclampsia cases relative to controls." (PMID 36914823, 2023).